RN7SKP126 (RN7SK pseudogene 126)
Gene: Miscellaneous RNA gene on chromosome 1 (192,875,686 to 192,875,985, reverse strand). Ensembl gene ENSG00000223075.
Homologues: Orthologues: chimpanzee 7SK (92% identical). Paralogues in human: RN7SKP124 (72% identical), RN7SKP44 (72% identical), RN7SKP203 (71% identical), RN7SKP25 (71% identical), RN7SKP255 (71% identical), 7SK (71% identical), RN7SKP180 (71% identical), RN7SKP211 (71% identical), RN7SKP176 (71% identical), RN7SKP243 (71% identical), RN7SKP72 (71% identical), RN7SKP9 (71% identical), and 284 more.